NRG1 (neuregulin 1)
Diseases named in the same sentence as NRG1 in open-access papers (continued):
Sharing a sentence is not in itself a finding about the gene and the disease.
schizophrenia (continued). "Taken together, these studies support a potential mode of therapeutic action for antipsychotics via NRG1–ErbB4 signaling which contributes to treatment efficacy in controlling schizophrenia symptoms." (PMID 35337293, 2022). "NRG1 is fundamental in schizophrenia progression, and was found significantly upregulated in the brain of schizophrenic patients." (PMID 36460658, 2022). "To verify the importance of high mPFC NRG1 level in FGR induced schizophrenia progression, we constructed a shNRG1 lenti-virus." (PMID 36460658, 2022). "Postmortem studies have shown that schizophrenia patients have a decreased cortical NRG-1 expression." (PMID 36620856, 2022). "Neuregulin-1 (NRG-1) gene and its receptor erb-b2 receptor tyrosine kinase 4 (erbB4) are significant risk factors for schizophrenia." (PMID 36620856, 2022). "Collectively, these results indicated that mPFC NRG1 knockdown rescued schizophrenia behaviors in FGR mice." (PMID 36460658, 2022). "NRG-1 or erbB4 knock out mice exhibit schizophrenia-like behaviors such as disruption of PPI, latent inhibition and cognitive deficits." (PMID 36620856, 2022). "And the mRNA and protein level of neuregulin 1(NRG1), which is a critical schizophrenia gene, increased significantly in FGR mouse mPFC." (PMID 36460658, 2022). "Our study suggests PFC NRG-1 alteration as a potential mechanism in schizophrenia-like behaviors in the NVHL model." (PMID 36620856, 2022). "Both overexpression and knockout NRG-1 signaling have induced schizophrenia-like behaviors in animals." (PMID 33708250, 2021). "To address the cell-type-specific alteration of Nrg1 gene expression in the postmortem PFC of schizophrenia patients, we analyzed the GEO database GSE9357721 and GSE9398722." (PMID 33436636, 2021). "With the development of molecular genetics, many genes are related to schizophrenia, of which the most supportive gene is NRG1." (PMID 33897409, 2021). "Together, these results suggest that type I Nrg1 expression is increased in GABAergic interneurons from the postmortem PFC of schizophrenia patients." (PMID 33436636, 2021). "While the function and processing of NRG3 have not been studied as well as its NRG1 homolog, their overlaps in similarity and function allow researchers to identify the roles of NRG3 identical to those of NRG1 in schizophrenia." (PMID 33897409, 2021). "Although NRG-1 protein has been implicated in neurodevelopment, myelination, and schizophrenia, a definite role for NRG-1 in schizophrenia remains questionable." (PMID 33708250, 2021). "NRG1 suppresses NMDAR activation in the prefrontal cortex in subjects with schizophrenia, consistent with the increased NRG1-ErbB4 signaling observed in this disease." (PMID 33552387, 2021). "Neuregulin 1 (NRG1) and its receptor ErbB4 represent schizophrenia-associated susceptibility factors that closely interact with NMDAR." (PMID 34899420, 2021). "Type I Nrg1 mRNA levels were significantly increased in GABAergic interneurons from schizophrenia PFC, compared with age- and sex-matched controls." (PMID 33436636, 2021). "Patients with schizophrenia have disturbances in neuregulin-1 (NRG1) and its receptor tyrosine kinase ErbB4." (PMID 33552387, 2021). "To mimic the increased type I Nrg1 expression in GABAergic interneurons from schizophrenia patients, we aim to generate Nrg1 transgenic mice that overexpress type I Nrg1 specifically in GABAergic interneurons." (PMID 33436636, 2021). "Further investigations have suggested potential protective properties though the modulation of Neuregulin 1 (Nrg1), another gene related to schizophrenia and cannabis-induced neuropsychiatric effects." (PMID 34360626, 2021). "To mimic increased expression of Nrg1, a schizophrenia susceptibility gene in GABAergic interneurons from patients with schizophrenia, we generated gtoNrg1 mice with overexpression of Nrg1 in GABAergic interneurons." (PMID 33436636, 2021).
schizophrenia (continued). "Studies suggest that NRG1/ErbB4 interactions play a vital role in the pathological mechanism of schizophrenia." (PMID 33897409, 2021). "Both NRG1 and ErbB4 are risk genes for brain disorders including major depressive disorder (MDD) and schizophrenia (SZ)." (PMID 33854034, 2021). "Mutant mice heterozygous for either Nrg1 or its receptor, Erbb4, show a behavioral phenotype that overlaps with mouse models for schizophrenia." (PMID 34072341, 2021). "A possible relationship between the deregulation of NRG1 and schizophrenia is documented in a meta-analysis study." (PMID 33585010, 2020). "For instance, differential regulation of neuregulin 1 (NRG1) in schizophrenia is controlled by several 5′ SNPs that create/abolish binding sites for a string of transcription factors including SRF." (PMID 33520984, 2020). "Thousands of loci on the genome have been identified to be associated with schizophrenia, e.g. ANK3, ZNF804A, CACNA1C, NRG1, TCF4, and MHC region, etc." (PMID 30508120, 2019). "Supporting our findings, activation of NRG1-ErbB4 signaling was neuroprotective, which was mediated by enhancing GABAergic transmissions in ischemic brain injury and schizophrenia." (PMID 31560696, 2019). "We used an anti-Neuregulin1 (anti-Nrg1) antibody to induce schizophrenia-like phenotypes, including hyperlocomotion and impaired prepulse inhibition." (PMID 31653237, 2019). "Mutations of the ERBB4 gene differentially affected the treatment response to paliperidone in individuals with schizophrenia, implicating the neuregulin 1 (NRG1)–ErbB4 pathway for modulating the antipsychotic response." (PMID 30508120, 2019). "Recent genetic studies have demonstrated a possible role of neuregulin 1 and its receptor erbB in the pathophysiology of schizophrenia." (PMID 30890939, 2019). "Previous works showed that administration of anti-Nrg1 antibodies induced schizophrenia-like behavioral phenotypes (including hyper-locomotion and impaired pre-pulse inhibition of startle) and altered synaptic transmission in adult mice." (PMID 31653237, 2019). "NRG1 was one of the first schizophrenia candidate genes to be identified using molecular genetic methods at a genomic locus defined by linkage analysis studies in family pedigrees." (PMID 29520222, 2018). "For example, disrupted in schizophrenia 1 (DISC1), neuregulin 1 (NRG1) and CACNA1C mutations and polymorphisms are known to be associated with schizophrenia, bipolar disorder and major depression." (PMID 29794033, 2018). "Anti-NRG1 treated mice display motor abnormalities, as well as certain schizophrenia-like behavioral alterations, and impaired synaptic transmission." (PMID 29844389, 2018). "While genetic studies link NRG1 and its receptor ERBB4 to schizophrenia and other brain disorders, how NRG1 dysfunction impacts brain function is not fully understood." (PMID 29844389, 2018). "The findings are also relevant to the possible role of NRG1 signaling in the pathophysiology of schizophrenia or other disorders affecting this brain region." (PMID 30348978, 2018). "NRG1 and the gene encoding its receptor, ERBB4, are risk genes for schizophrenia, although how alterations in these genes disrupt their function has not been fully established." (PMID 29844389, 2018). "Our study was set to examinethe effects of DMS treatment on schizophrenia-like behaviors, as well as the expression of NRG1 in brain areas relevant to schizophrenia." (PMID 30574102, 2018). "One putative risk gene is neuregulin 1 (NRG1), which signals via the receptor tyrosine kinase ErbB4, itself a schizophrenia risk gene." (PMID 29740596, 2018). "EGR3 is a member of the Egr family of immediate early gene zinc finger transcription factors, and is activated downstream of numerous schizophrenia candidate proteins, including NRG1, NMDAR and CN." (PMID 29520222, 2018). "A post-mortem study of schizophrenia found elevated NRG1 and ErbB4 proteins in the prefrontal cortex." (PMID 30574102, 2018).
schizophrenia (continued). "In the nervous system, NRG1 is thought to signal mainly through the ErbB4 receptor, and both NRG1 and ERBB4 have been genetically linked to schizophrenia." (PMID 29844389, 2018). "In terms of genetic-structural MRI studies, “patients with schizophrenia are found to have reductions in the frontal, temporal, parietal cortices, and limbic regions, which are associated with BDNF, COMT, and neuregulin-1 (NRG1) genes”." (PMID 30349492, 2018). "Overall, our results indicate that stabilization of NRG1 by anti-NRG1 activates receptor-independent signaling leading to increased phosphorylation of cofilin, synaptic dysfunction, and schizophrenia-relevant behavioral changes in mice." (PMID 29844389, 2018). "It was recently shown that inducible overexpression of NRG1 in CAMK2a+ excitatory neurons results in impaired glutamatergic transmission and schizophrenia-related behavioral alterations, which are reversed when the NRG1 transgene is turned off." (PMID 29844389, 2018). "Studies have demonstrated an association between schizophrenia and d-amino acid oxidase (DAO), DAO activator (DAOA)/G72, and neuregulin 1 (NRG1) single-nucleotide polymorphisms (SNPs)." (PMID 29326614, 2017). "Genetic, post-mortem and neuroimaging studies repeatedly implicate neuregulin-1 (NRG1) as a critical component in the pathophysiology of schizophrenia." (PMID 28094814, 2017). "Herein, we examined in whole blood, several NRG1 mRNA isoforms, and NRG1-β1 protein levels in serum within those with schizophrenia compared to healthy controls." (PMID 29225331, 2017). "This study is the first to associate these novel physiological mechanisms, previously independently identified as being abnormal in schizophrenia, with disruption of NRG1 function." (PMID 28338897, 2017). "As a transmembrane protease, BACE1 is important for several disease-related substrates, including beta amyloid peptide production in AD and NRG1 in schizophrenia." (PMID 28993723, 2017). "However, whether NRG1 genetic variations directly cause brain structural and functional changes in schizophrenia remains unclear and further studies in schizophrenic patients with neuroimaging in combination with other disease-specific biomarkers would be helpful." (PMID 28993723, 2017). "Deficits in neurite outgrowth, possibly involving dysregulation of risk genes neuregulin-1 (NRG1) and disrupted in schizophrenia 1 (DISC1) have been implicated in psychiatric disorders including schizophrenia." (PMID 28198409, 2017). "Several human postmortem brain studies have shown dysregulation of gene expression of NRG1, ErbB4 or down-stream targets among individuals with schizophrenia." (PMID 29163244, 2017). "Post-mortem human brain studies in schizophrenia have shown differential expression of NRG1 mRNA and protein in various brain regions, most notably in dorsolateral prefrontal cortex and hippocampus, although other studies of both regions have been negative." (PMID 29225331, 2017). "Investigation of peripheral gene expression patterns of transcripts within the NRG–ErbB signaling pathway, other than neuregulin-1 (NRG1), among patients with schizophrenia and more specifically treatment-resistant schizophrenia (TRS) is limited." (PMID 29163244, 2017). "Nevertheless, the bulk of the evidence to date suggests NRG1 remains an important target for schizophrenia research." (PMID 29225331, 2017). "We are aware of two previous studies that have examined peripheral NRG1 protein levels in schizophrenia." (PMID 29225331, 2017). "In future studies, it will be important to investigate BACE1, Nrg1-related molecular pathways, and neural circuits in endophenotypes resembling features of schizophrenia." (PMID 28993723, 2017). "In this section, we will focus on the function of BACE1-dependent NRG1 cleavage in schizophrenia clinical studies." (PMID 28993723, 2017).
schizophrenia (continued). "In general, our results support the notion posed by previous peripheral blood and post-mortem brain studies that NRG1 transcription is dysregulated in schizophrenia and perhaps more specifically treatment-resistant schizophrenia." (PMID 29225331, 2017). "While hypo-function of Nrg1 is linked to schizophrenia-like behaviors in BACE1-null mice, enhanced expression of either BACE1-cleaved Nrg1-ntf fragment or of full-length Nrg1 surprisingly also induces schizophrenia-like behaviors." (PMID 28469554, 2017). "Accordingly, we have previously found that expression of neuregulin 1 (NRG1), a schizophrenia risk gene, is significantly decreased in asphyxia-induced rats." (PMID 29163023, 2017). "In contrast to the increase in NRG1 mRNAs, we found that NRG1-β1 protein levels were lower in schizophrenia patients compared to healthy controls (P = 0.019) but after adjustment for smoking status, this finding was attenuated (P = 0.050)." (PMID 29225331, 2017). "Our results represent the first comprehensive investigation of NRG1 isoforms and protein expression in the blood of clozapine-treated schizophrenia patients and suggest levels of some NRG1 transcripts are upregulated in those with schizophrenia." (PMID 29225331, 2017). "The aim of this study was to address these gaps in the current literature by investigating peripheral mRNA and protein levels of NRG1 in schizophrenia, as peripheral measures have the potential to serve as biomarkers in the clinical setting." (PMID 29225331, 2017). "Due to various BACE1 substrates, it is helpful to investigate their role and further illustrate the function of Nrg1 downstream signaling pathways in schizophrenia." (PMID 28993723, 2017). "To our knowledge, we are the first to report elevated levels of NRG1 EGFα, EGFβ, and type I(Ig2) in schizophrenia, specifically in those with treatment-resistant schizophrenia." (PMID 29225331, 2017). "Our results highlight the importance of genetic variation at both the 5′ and 3′ ends of NRG1 and provide justification for further investigation of NRG1’s role in the pathophysiology of schizophrenia." (PMID 28094814, 2017). "Despite these limitations, the current study represents the first comprehensive investigation of NRG1 isoforms and protein expression in whole blood of clozapine-treated schizophrenia patients." (PMID 29225331, 2017). "Here, we will discuss the relationship between NRG1 gene and a few specific endophenotypes of schizophrenia." (PMID 28993723, 2017). "The abnormal behaviors were Nrg1-ntfβ-specific since turning off the Nrg1-ntfβ expression genetically can reverse the schizophrenia-like behaviors in the mouse model." (PMID 28993723, 2017). "Later, studies on SNP8NRG221533 in schizophrenia showed that the NRG1 variation was related to decreased anterior cingulum fractional anisotropy, lower volume of internal capsule, and reduced volume of left UF." (PMID 28993723, 2017). "Our review will provide a better understanding of Nrg1 in schizophrenia and a potential strategy for using BACE1 cleavage of Nrg1 as a unique biomarker for diagnosis, as well as a new therapeutic target, of schizophrenia." (PMID 28993723, 2017). "Previous postmortem studies have shown increased NRG1 mRNA levels in the hippocampus and prefrontal cortex of schizophrenia patients compared to that of healthy controls." (PMID 29326614, 2017). "Numerous studies have suggested a genetic predisposition to schizophrenia, and many genes, including DISC1, catechol-O-methyltransferase (COMT), neuregulin 1 (NRG1), and DTNBP1, have been identified as candidate susceptibility genes." (PMID 28937620, 2017). "Mutant mice containing disruption of the transmembrane (TM) domain of the NRG1 gene constitute a heuristic model for dysregulation of NRG1-ErbB4 signaling in schizophrenia." (PMID 28338897, 2017).
schizophrenia (continued). "This is in line with clinical observations that increased Nrg1 or ErbB4 transcripts and proteins are found in schizophrenia patients, supporting the importance of balanced BACE1-cleaved Nrg1 in synaptic functions." (PMID 28469554, 2017). "Spironolactone's effect was biochemically validated both in vitro and in vivo, and it was found to improve schizophrenia‐relevant behavioral deficits in a Nrg1 transgenic mouse model." (PMID 28743784, 2017). "This is the first report to examine the effect of olanzapine in a combined model of schizophrenia (NRG1 knockout and PCP)." (PMID 26781398, 2016). "Employing a mouse schizophrenia model established by neonatal neuregulin-1 challenge, we analysed postpubertal consequence of the NRG1 pretreatment for the electrophysiological property of nigral dopamine neurons." (PMID 26935991, 2016). "Neuregulin 3 (NRG3), a paralog of NRG1, is a molecule of increasing interest, due to its link to psychiatric disorders that includes schizophrenia." (PMID 26877878, 2016). "Various NRG1 knockout and transgenic mouse lines have been developed to study the relationship between altered NRG1 signalling and impact on behavioural and brain endophenotypes relevant to schizophrenia." (PMID 27725886, 2016). "It is noteworthy that the opioid-induced and NRG1-induced schizophrenia-like behaviours both involve disinhibition of GABA inputs to midbrain dopaminergic neurons." (PMID 26935991, 2016). "As for other schizophrenia related genes, an elevated Nrg1 gene expression level was found in the present study in PFC of young adult P2rx7+/+ animals after PCP treatment." (PMID 27824163, 2016). "Neuregulin1 (NRG1) plays diverse developmental roles and is likely involved in several neurological disorders including schizophrenia." (PMID 27364328, 2016). "Other studies have shown that hyperactivity and increased locomotion in NRG1 heterozygous mice can be reversed with clozapine (an antipsychotic to treat schizophrenia) and environmental enrichment." (PMID 27047540, 2016). "in their study, showed a significant ‎association between schizophrenia and SNP8NRG241930 of NRG1 (located at the 5′ end of ‎this gene) in an Iranian population." (PMID 27928246, 2016). "This level of genetic complexity highlights the difficulty associated with generating accurate preclinical genetic models of NRG1 dysfunction in schizophrenia." (PMID 27725886, 2016). "Together these findings identify novel neuroprotective effects of NRG-1, providing a potential mechanistic link between impaired NRG-1 signaling and neurological disorders such as schizophrenia." (PMID 27057274, 2016). "The association between NRG1 and superior temporal gyrus (STG) anatomy ‎was explored in patients with schizophrenia." (PMID 27928246, 2016). "Biochemical and physiological influences of NRG1 have been intensively investigated in GABAergic cell populations, and such studies have implicated dysregulation of GABAergic transmission in the pathophysiology of schizophrenia, supporting the ‘GABA hypothesis’." (PMID 26935991, 2016). "Many studies using mouse models of NRG1 and ErbB4 have shown schizophrenia-related behaviors that can be reversed using antipsychotic drugs." (PMID 26733804, 2015). "Post-mortem brain analyses and some genetic studies have reported interneuronal deficits and involvement of the DISC1, NRG1 and ErbB4 genes in schizophrenia, respectively." (PMID 26656849, 2015). "Several studies reported the association between PPI in schizophrenia and HT2AR, COMT, NRG1 and RELA, which also directly or indirectly influence glutamatergic signaling." (PMID 25768306, 2015). "Similar results were obtained after PFC perturbations in rats and in DISC1 and neuregulin-1 mouse models of schizophrenia (for review see47, 64)." (PMID 26608841, 2015). "Several genetic linkage studies have shown Neuregulin1 (NRG1) as a strong candidate gene for schizophrenia." (PMID 25805966, 2015).